IFT54 (intraflagellar transport 54)
Description:
Plays an inhibitory role on IL13 signaling by binding to IL13RA1. Involved in suppression of IL13-induced STAT6 phosphorylation, transcriptional activity and DNA-binding. Recruits TRAF3 and DISC1 to the microtubules. Involved in kidney development and epithelial morphogenesis. Involved in the regulation of microtubule cytoskeleton organization. Is a negative regulator of microtubule stability, acting through the control of MAP4 levels. Involved in ciliogenesis (By similarity).
Synonyms: MIP-T3; TRAF3IP1; MIPT3; DKFZP434F124; FAP116; CFAP116; SLSN9
Tractability: PROTAC: ubiquitination databases record sites on it.
Gene: Protein-coding gene on chromosome 2 (238,320,441 to 238,402,114, forward strand). Ensembl gene ENSG00000204104.
Subcellular location: Cytoplasm, cytoskeleton; Cell projection, cilium; Cytoplasm, cytoskeleton, cilium axoneme; Cytoplasm, cytoskeleton, cilium basal body
Subcellular location (Human Protein Atlas): Nuclear bodies; Primary cilium transition zone; Nucleoli fibrillar center; Nucleoplasm
Pathways (Reactome):
Organelle biogenesis and maintenance: Intraflagellar transport
Gene Ontology:
Molecular function: protein binding; microtubule binding
Biological process: kidney development; morphogenesis of a polarized epithelium; negative regulation of defense response to virus; negative regulation of protein phosphorylation; negative regulation of protein-containing complex assembly; negative regulation of type I interferon production; regulation of microtubule cytoskeleton organization; cilium assembly; intraciliary anterograde transport; intraciliary transport; animal organ development; system development
Cellular component: ciliary base; ciliary tip; ciliary transition zone; intraciliary transport particle A; intraciliary transport particle B; axoneme; ciliary basal body; cilium; centrosome; cytoskeleton; intraciliary transport particle
Genetic constraint (gnomAD): Loss-of-function variants: 47 observed, 82.91 expected, observed/expected ratio (o/e) 0.57, 90% interval 0.45 to 0.72. The upper end of that interval is the gene's LOEUF score, 0.72, which puts it in group 2 of 6, group 1 being the genes least tolerant of losing a copy. Missense variants: 769 observed, 817.52 expected, observed/expected ratio (o/e) 0.94, 90% interval 0.89 to 1. Synonymous variants: 301 observed, 304.04 expected, observed/expected ratio (o/e) 0.99, 90% interval 0.9 to 1.09.
Homologues: Orthologues: chimpanzee TRAF3IP1 (99% identical), macaque TRAF3IP1 (96% identical), dog TRAF3IP1 (78% identical), rat Traf3ip1 (74% identical), mouse Traf3ip1 (71% identical), guinea pig TRAF3IP1 (67% identical), pig TRAF3IP1 (67% identical), tropical clawed frog traf3ip1 (48% identical), zebrafish traf3ip1 (47% identical), Drosophila melanogaster IFT54 (23% identical), Caenorhabditis elegans dyf-11 (21% identical).
Diseases named in the same sentence as IFT54 in open-access papers:
IFT54 is named in the same sentence as 30 diseases in open-access papers, as found by Europe PMC text mining. Sharing a sentence is not in itself a finding about the gene and the disease. The quoted sentences say what the papers report.
ciliopathy (8 papers, 2015 to 2025). A genetic disorder of the cellular cilia or the cilia anchoring structures, the basal bodies, or of ciliary function. "It is interesting to note a case study that reported five unrelated families (eight patients) of nephronophthisis (NPHP)-related ciliopathies with IFT54 variations; NPHP is a relatively mild ciliopathy compared with skeletal ciliopathies." (PMID 37309605, 2023). "Impaired IFT54 function led to overexpression of the microtubule associated protein MAP4 and lowering MAP4 expression rescued polarity defects in vitro and partially rescued ciliopathy phenotypes in zebrafish morphants." (PMID 34055783, 2021). "Interestingly, ciliopathy conditions were associated with increased stability of cytoplasmic microtubules, a phenotype which was more deeply investigated in the context of NPH and TRAF3IP1/IFT54 mutant conditions." (PMID 34055783, 2021). "Our findings highlight the regulation of cytoplasmic microtubule dynamics as a role of the IFT54 protein beyond the cilium, contributing to the development of NPH-related ciliopathies." (PMID 26487268, 2015).
IFT54 also shares sentences with these, for which no sentence is quoted: nephronophthisis (4 papers); cancer (3); Senior-Loken syndrome (3); tumor (3); infection (2); Obesity (2); retinal degeneration (2); Astigmatism (1); Bardet-Biedl syndrome (1); Cerebellar atrophy (1); cholestasis (1); cyst (1); developmental delay (1); fibrosis (1); fungal infection (1); genetic disease (1); Hepatic fibrosis (1); hypogonadism (1); Intellectual disability (1); Jeune syndrome (1); Joubert syndrome (1); kidney disease (1); liver cancer (1); Mainzer–Saldino syndrome (1); microphthalmia (1); orofaciodigital syndrome (1); Pigmentary retinopathy (1); schizophrenia (1); Senior-Løken syndrome (1).